ALK (ALK receptor tyrosine kinase)
Diseases named in the same sentence as ALK in open-access papers (continued):
Sharing a sentence is not in itself a finding about the gene and the disease.
neuroblastoma (continued). "We investigated ALK, STAT3 and MYCN levels in CLB-GE, CLB-BAR, Kelly and CLB-GA neuroblastoma cell lines upon treatment with STAT3 inhibitors." (PMID 23889739, 2013). "The recently demonstrated functional and synergistic relationship between MYCN and ALK, another important oncogene in neuroblastoma, further reinforces the central role of MYCN in neuroblastoma oncogenesis." (PMID 23308108, 2013). "Left nephrectomy with adrenalectomy revealed stroma-poor, undifferentiated neuroblastoma with regional node involvement and multiple segmental chromosomal aberrations, including 1p and 3p loss, but no MYCN or ALK alterations." (PMID 41749639, 2026). "Conversely, a 2023 abstract described a patient with ALK-positive paraspinal neuroblastoma and no prior history of diabetes, who developed DKA 14 months after starting lorlatinib." (PMID 41322009, 2025). "This is a novel liquid biopsy–based in-time monitoring concept for infants and children with TERT-rearranged neuroblastoma with and without additional mutations in the RAS/MAPK/ALK signaling network." (PMID 39760332, 2025). "The neuroblastoma cell line NGP demonstrated moderate ALK surface expression (ALK WT, MYCN non-amplified; geometric mean 8.6x IgG control) and there was minimal detection of expression in the NGP ALK KO cell line (geometric mean 1.6x IgG control)." (PMID 40813394, 2025). "MYCN tumors resembled adrenergic, while ALK/MYCN tumors resembled mesenchymal, neuroblastoma." (PMID 38451815, 2024). "However, inhibiting ALK suppressed this pathway, hindering NEPC and neuroblastoma growth in lab experiments and live models." (PMID 38397899, 2024). "Several RTKs, including ALK, KIT, MET, NTRK2, and RET, play a major role in neuroblastoma pathogenesis, and their activation could be responsible for adaptive resistance to trametinib and ganitumab in neuroblastoma." (PMID 39001383, 2024). "Although the combination of lorlatinib with ALK.CAR‐Ts enhanced anti‐tumour activity, neuroblastoma tumours with low ALK expression were not fully eradicated." (PMID 38877641, 2024). "Genomics are central for management; diagnosing ALK-positive neuroblastoma triggers consideration of ALK-targeted therapy, which is not relevant for PPGL." (PMID 39548528, 2024). "Therefore, we will focus on the roles of ALK and PIM in neuroblastoma, their critical signalling nodes, and regulation of cellular metabolism." (PMID 37414143, 2023). "In neuroblastoma, several studies combining high-throughput proteomics and RNA-sequencing techniques identified ERK1/2 and Akt as major downstream effector kinases of full-length ALK." (PMID 37414143, 2023). "Specifically, a recent phase I clinical study provided insights into the safety and potential efficacy of lorlatinib, a third-generation ALK inhibitor, both with and without chemotherapy, for the treatment of ALK-driven refractory or relapsed neuroblastoma." (PMID 37998328, 2023). "Patients whose tumors harbored ALK amplification had worse overall survival, supporting the notion that these tumors constitute a highly aggressive subtype of neuroblastoma." (PMID 36807339, 2023). "Pre-clinical studies have successfully demonstrated that ALK can be targeted using CAR T-cell immunotherapy, although cell surface levels may be too low in some neuroblastomas for productive engagement by some CAR-targeting moieties." (PMID 36831514, 2023). "Taken together, these results suggest that dual inhibition of ALK and SHP2 could be an effective treatment strategy for neuroblastoma tumors harboring ALK aberrations." (PMID 38032104, 2023). "The ALK gene is situated in proximity to MYCN and ALKAL2 on chromosome 2p and it has been argued that co-amplification of these three explains the inferior outcome in neuroblastoma patients with 2p gain." (PMID 35362827, 2022).
neuroblastoma (continued). "In contrast to our observations of ALK mutations co-occurring with NF1 or activating RAS mutations, these mutations were mutually exclusive in neuroblastoma samples from patients not treated with ALK inhibitors." (PMID 35689207, 2022). "While some of the roles that ALK and a few other RTK family members play in neuroblastoma initiation, progression, or aggressiveness have been examined, the rationale for such studies has usually been linked to known functions of such genes in other cancer paradigms." (PMID 34716856, 2022). "We found that expression of ALK and PIK3CA were positively correlated in neuroblastoma samples." (PMID 36585695, 2022). "Ceritinib is a small molecule ALK TKI that has demonstrated efficacy in ALK-positive tumors including ALCL, inflammatory myofibroblastic tumor, neuroblastoma, and rhabdomyosarcoma; in ALK+ ALCL, the most commonly reported complication was elevated transaminases." (PMID 35211406, 2022). "Encouragingly, we showed that p110α inhibitors promote the suppressive effects of ALK inhibitors in neuroblastoma, so the presence of PI3K inhibitors may help to antagonize the drug resistance of neuroblastoma." (PMID 36585695, 2022). "While the ALK protein expression in alveolar rhabdomyosarcoma and neuroblastoma correlates frequently with ALK copy number gains, none of angiomatoid fibrous histiocytoma showed this feature." (PMID 34228212, 2022). "We focused on the ALK, IGF1, WNT, EZH2/PRC2, BET, CDK7, and CDK12/13 signaling pathways since they have been shown to be important during the normal development of sympathoadrenal cells and/or involved in neuroblastoma tumorigenesis." (PMID 35681734, 2022). "In fact, overexpression of FAM150B in the Th-Mycn neuroblastoma mouse model (which has no ALK-activating mutations) induced tumours that are sensitive to tyrosine kinase inhibitor (TKI) treatment, while ALK mutations confer resistance." (PMID 34769149, 2021). "In neuroblastoma cells, this leads to increased tyrosine phosphorylation of p190 RhoGAP, GIT1, and DNER, and it has been proposed that the PTN inhibitory effect on PTPRZ1 acts as a major ALK indirect activating mechanism." (PMID 34957126, 2021). "This could potentially be due to intrinsic differences in protein expression and activity levels in the neuroblastoma cells and/or differential expression of known neuroblastoma oncogenes such as MYCN or ALK." (PMID 33889818, 2021). "The anaplastic lymphoma kinase (ALK) and rearranged during transfection (RET) receptor tyrosine kinases (RTKs) are expressed in both the developing neural crest and the pediatric cancer neuroblastoma." (PMID 33921066, 2021). "It is now well accepted that ALK and MYCN cooperate to drive neuroblastoma." (PMID 34885007, 2021). "Regardless of amplification, ALK overexpression is widely observed in nearly 100% of basal cell carcinoma and in more than 50% of neuroblastoma, with only 10% of primary neuroblastoma." (PMID 34199079, 2021). "Trk receptors are therefore considered an attractive target for targeted therapies, with the selective Trk inhibitor, lestaurtinib, and pan-ALK/Trk/ROS1 inhibitor, entrectinib, showing favourable preclinical and phase 1 clinical results for relapsed/refractory neuroblastoma tumours." (PMID 34064704, 2021). "Whereas heparins with short chain lengths bound to ALK in a monovalent manner did not activate the receptor, longer heparin chains induced ALK dimerization and activation in cultured neuroblastoma cells." (PMID 33466277, 2021). "Furthermore, they showed that neuroblastoma cell lines express ALKAL2 protein, identifying a potential autocrine/paracrine activation of ALK in a tumor setting." (PMID 34885007, 2021). "ALK is a member of the insulin receptor tyrosine kinase (RTK) superfamily, for which high expression levels are usually confined to neurons during nervous system development, although it can also be highly expressed in neuroblastoma tumours." (PMID 34064704, 2021).
neuroblastoma (continued). "Indeed, two new ADCs have been recently deployed to target ALK and GPC2 expressed on the surface of neuroblastoma cells." (PMID 33076448, 2020). "Here, ETV5 expression was significantly elevated in ALKmut neuroblastomas compared to tumours harbouring ALKwt or lacking ALK amplifications." (PMID 31937834, 2020). "In ALK-activating neuroblastoma cellular backgrounds, the effects of ETV5 reduction on MEK inhibition were significant, albeit attenuated when compared to the same cell lines treated with ALK inhibitor." (PMID 31937834, 2020). "Moreover, protein expression of ALK, MEK6 and GATA3 was increased after regorafenib treatment, suggesting potential mechanisms for neuroblastoma cell resistance to regorafenib." (PMID 32457362, 2020). "Taken together, our data highlight ETV5 as an intrinsic component of oncogenic ALK-driven signalling through the MAPK axis and propose that ETV5 upregulation in neuroblastoma may contribute to tumour aggressiveness." (PMID 31937834, 2020). "Neuroblastoma patients exhibit de novo resistance to many existing ALK inhibitors, and no clinical therapeutics to target MYCN have yet been developed." (PMID 35582571, 2019). "We describe a mechanistic interaction in which ALK upregulates MYCN transcription, and discuss clinical trials emerging to develop transcriptional inhibitors of MYCN, and to identify effective inhibitors of ALK in neuroblastoma patients." (PMID 35582571, 2019). "The type of ALK-expressing tumor (ALCL, IMT, NSCLC, neuroblastoma, melanoma, etc.)and possible concomitant activation of oncogenes, such as MYCN or K-RAS in neuroblastomas, for example, are also determinant for the choice of one particular signaling pathway by tumor cells." (PMID 30813562, 2019). "Indeed, we observed that a treatment combining P36 with the ALK-specific inhibitor crizotinib resulted in additive cytotoxicity in ALK-bearing tumor cells in vitro in two cell models, ALCL, and neuroblastoma." (PMID 30813562, 2019). "Although no clinical trials have yet been initiated, human anti-ALK CAR T cells were shown to eradicate ALK-positive neuroblastoma tumors in a xenogeneic immunodeficient murine model." (PMID 31847387, 2019). "Altogether, these data suggest that upon treatment with the recently described ALK TKI repotrectinib, growth of ALK-driven neuroblastoma cells and xenografts are inhibited, suggesting that repotrectinib should be further explored in a neuroblastoma setting." (PMID 31852910, 2019). "Also the few neuroblastoma driver genes that were identified so far, including MYCN, ALK, PHOX2B and LIN28B, are all involved in early stages of the sympathetic nervous system development with both LIN28B and MYCN implicated as major drivers of stemness." (PMID 30504901, 2018). "ALK+ ALCL should be distinguished from ALK+ large B-cell lymphomas and nonhematopoietic neoplasms expressing ALK such as inflammatory myofibroblastic tumors, rhabdomyosarcomas, and neuroblastomas." (PMID 29617304, 2018). "Previous studies have shown that ALK inhibition synergizes with chemotherapy or CDK4 inhibition in preclinical models of neuroblastoma, and a clinical trial (NCT02780128) for testing the combination of ceritinib and ribociclib in ALK-mutant neuroblastoma patients is ongoing." (PMID 28425916, 2017). "Given the improved in vitro efficacy of combined ALK and MDM2 inhibition, we next determined whether ceritinib in combination with CGM097 was effective in the neuroblastoma mouse xenograft models." (PMID 28425916, 2017). "Previous preclinical work has shown that crizotinib inhibited growth of neuroblastoma xenografts expressing ALK R1275Q or amplified wild-type ALK, but failed to inhibit growth of xenografts harboring F1174L-mutated ALK." (PMID 28425916, 2017). "From the ALK kinase domain, two HLA-A2.1 restricted CD8+ T-cell epitopes, p280–289 (SLAMLDLLHV) and p375–389 (GVLLWEIFSL) were identified and confirmed to be immunogenic in HLA-matched ALCL and neuroblastoma cell lines." (PMID 29189709, 2017).
neuroblastoma (continued). "For MYCN, non-amplified stage 4 neuroblastoma, neurotrophic tyrosine kinase 1, or ALK paired with GFRA2, GFRA3, SSK1, GPR173, or with one another provided the most promising paired-hits." (PMID 28871274, 2017). "ALK copy numbers detected by ddPCR of plasma-derived cfDNA have not yet been reported for patients with neuroblastomas." (PMID 29156716, 2017). "Anaplastic Lymphoma Kinase (ALK) is a transmembrane receptor kinase that belongs to the insulin receptor superfamily and has previously been shown to play a role in cell proliferation, migration and invasion in neuroblastoma." (PMID 27888620, 2016). "Inhibition of ALK using TAE684 is able to overcome this resistance in a synergistic fashion, a finding that could be highly relevant for improvement of neuroblastoma therapy." (PMID 27655666, 2016). "A recent trial of crizotinib in ALK-positive pediatric cancers demonstrated excellent activity in pediatric ALCL, where the NPM-ALK fusion protein is the major driver, but suboptimal activity in neuroblastoma." (PMID 27049722, 2016). "In our previous analyses of mutant ALK reported from neuroblastoma patients, we have observed that not all of those tested that gave rise to foci in NIH3T3 transformation assays also exhibit Ba/F3 transforming potential." (PMID 27483357, 2016). "Therefore we examined the therapeutic effect of brigatinib as a single agent in BalbC/NUDE mice injected with human neuroblastoma CLB-BAR cells, (ALK Δ4-11 and MYCN amplified, ALK addicted) subcutaneously." (PMID 27049722, 2016). "Neither brigatinib nor crizotinib was able to inhibit growth of the non-ALK addicted neuroblastoma cell lines, IMR32 and CLB-PE, indicating that neither brigatinib nor crizotinib inhibitor was toxic to cells at the levels employed." (PMID 27049722, 2016). "Furthermore, an analysis encompassing 491 cancer types identified ALK and CHD9 as highly expressed in neuroblastoma." (PMID 27009842, 2016). "In this study we show that PF-06463922 is a highly effective inhibitor in neuroblastoma cell lines, as well as in non-native (Ba/F3 and PC12) cell model systems that express neuroblastoma-specific ALK mutations." (PMID 27483357, 2016). "Although PPTP did not test crizotinib, ALK-mutant or ALK-amplified neuroblastoma xenografts included in the PPTP neuroblastoma panel were responsive to this agent." (PMID 26380223, 2015). "ALK drives tumorigenesis in several types of cancers, including ALCL and neuroblastoma." (PMID 25950466, 2015). "The effect of P36 was first assayed on ALCL and neuroblastoma, which harbor cases with and without oncogenic ALK." (PMID 25950466, 2015). "In addition, the ALK-derived 36-aa peptide (P36) enhanced the cytotoxic effect of the ALK kinase inhibitor crizotinib in ALK-positive ALCL and neuroblastoma cell lines." (PMID 25950466, 2015). "Like ALK, KIT is an emerging marker for aggressive neuroblastoma that leads to poor prognosis." (PMID 25884760, 2015). "Perhaps ALK-induced upregulation of TRKB, a protein shown to enhance the survival of neuroblastoma-derived cells, may act as a pro-survival factor in the context of MYCN-driven tumor development." (PMID 26222553, 2015). "Downstream signalling cascade of ALK signalling includes AKT, ERK1/2 and STAT3.Calcium phosphorylates three kinases (AKT, ERK and FAK) that are involved in the cell survival signalling in neuroblastoma." (PMID 26010602, 2015). "We show that in ALK-mutated, MYCN-amplified neuroblastoma cells, crizotinib alone does not affect mTORC1 activity as indicated by persistent RPS6 phosphorylation." (PMID 25228590, 2014). "Furthermore, our data provide evidence that activated ALK triggers RET upregulation in mouse sympathetic ganglia at birth as well as in murine and human neuroblastoma." (PMID 24811913, 2014). "Of note, the majority of ALK D5F3 IHC-positive neuroblastomas did not possess ALK genomic amplification." (PMID 25188507, 2014).
neuroblastoma (continued). "At present, compared to ALK immunohistochemical expression, ALK copy number status has not been as widely studied as a biomarker in neuroblastomas, probably because of the rarity of ALK genomic amplification (prevalence 5% or less)." (PMID 25188507, 2014). "Second, ALK functions as an oncogene and NF1 as a tumor suppressor in neuroblastoma." (PMID 24278035, 2013). "The low level of ALK expression in neuroblastoma cell lines did not allow us to follow internalization by immunofluorescence." (PMID 22479414, 2012). "Second, our results illustrated that ALKF1174L expression are not necessarily link to increased ALK phosphorylation in neuroblastomas." (PMID 22479414, 2012). "Since both agonist and antagonist mAb treatment induced ALK internalization in CHO, we next investigated whether these treatments resulted in down-regulation of the receptor in neuroblastoma cell lines." (PMID 22479414, 2012). "In neuroblastoma and mesothelioma, ERK5 is activated by PI3K/AKT signaling; in breast cancer, STAT3 enhances MEK5 expression; and in renal epithelial cells, TGFβ1-induced MEK5/ERK5 activation occurs through ALK and p38 MAPK, facilitating MEF2C-mediated transcription." (PMID 40672381, 2025). "Finally, a truncated form of ALK, lacking the extracellular domain, has also been detected in neuroblastoma cases." (PMID 38339401, 2024). "Similarly to the lymphoma subtype, both ALK-driven NSCLC and neuroblastoma, previously incubated with short-term TKIs (20 h of alectinib or lorlatinib for H3122 and 20 h of lorlatinib for CLB-Ga), were more susceptible to phagocytosis with anti-CD47 mAb during co-culture assay." (PMID 39767726, 2024). "Whether ALK has an effect on lipid metabolism in neuroblastoma in vivo, however, remains unknown, but is not entirely implausible when contextualising its downstream effectors." (PMID 37414143, 2023). "Some recent publications also mainly reported mechanisms involving epigenetic rewiring or overexpression of receptor tyrosine kinases other than ALK, as mechanisms rendering neuroblastoma cells independent of ALK signaling, but their clinical relevance remained elusive to date." (PMID 35689207, 2022). "ALK regulates several pathways involved in cellular survival, replication and apoptosis, including the PI3K/AKT/mTOR, MAPK and STAT3 pathways, and it contributes to initiation and progression of different human tumours and cell lines, such as lymphomas, neuroblastoma and NSCLC." (PMID 36230686, 2022). "Regardless of the importance of ALK in neuroblastoma, the cellular functions of full-length ALK in both physiological and oncogenic contexts are largely unknown." (PMID 36585695, 2022). "In general, ALK activates multiple signaling pathways, such as the PI3K-AKT, CRKL-C3G, MEKK2/3-MEK5-ERK5, JAK-STAT and MAPK signaling pathways 19, which involved in the initiation and progression of many different cancer types, including lymphomas, neuroblastoma and colorectal cancer." (PMID 33391411, 2021). "Owing to its specific binding, CCC-003 could be a novel therapeutic agent for ALK-positive neuroblastoma without significant side effects." (PMID 34591871, 2021). "However, elevated ALK activity occurs only in around 14% of high-risk neuroblastoma, suggesting that MYCN is not targetable through the ALK pathway in the majority of neuroblastoma cases." (PMID 32087738, 2020). "Furthermore, these peptides could trigger specific anti-ALK CLTs to lyses ALK-positive ALCL cells and neuroblastoma cells in an HLA-matched manner." (PMID 32059449, 2020). "However, the application of MEK inhibitors to treat ALK-activated neuroblastomas is not straightforward." (PMID 35582571, 2019). "Initial studies have identified synergistic combinations of ALK inhibitors with mTOR inhibitors and with CDK4/6 inhibitors, and these combinations may serve to overcome some of the limitations of single-agent ALK inhibitor treatment for neuroblastoma." (PMID 30384486, 2018).